MTOR (mechanistic target of rapamycin kinase)
Diseases named in the same sentence as MTOR in open-access papers (continued):
Sharing a sentence is not in itself a finding about the gene and the disease.
Sepsis (continued). "Here, we investigated the role of the mTOR pathway in CD4+ T-cell survival in a mouse model of rapidly progressive lethal sepsis induced by severe invasive candidiasis and explored the possible mechanism." (PMID 31668132, 2019). "Here, we further examined the mechanisms underlying the effect of SIRT3 on sepsis-induced AKI, by focusing on the potential involvement and modulation of autophagy by AMPK and mTOR." (PMID 30487750, 2018). "In conclusion, this study uncovered a potential mechanism underlying the protective role of SIRT3 against sepsis-induced AKI, that involved induction of autophagy through the AMPK/mTOR pathway." (PMID 30487750, 2018). "In the present study, the levels of calpain 1 and cleaved Atg5 and the phosphorylation/activity of mTOR were significantly increased in the livers of mice with sepsis." (PMID 30154452, 2018). "To explore the role of the mTOR pathway in sepsis-induced cardiac dysfunction, we used rapamycin to inhibit the mTOR signaling pathway." (PMID 30050390, 2018). "The mechanism underlying the protective effect of SIRT3 through modulation of autophagy was further investigated by assessing the levels of the autophagy regulators AMPK and mTOR in kidney tissues exposed to sepsis-induced AKI." (PMID 30487750, 2018). "Inhibition of the mTOR pathway has cardioprotective effects on myocardial dysfunction during sepsis induced by CLP, which is partly mediated through autophagy." (PMID 30050390, 2018). "Eight patients died (7 due to sepsis and 1 due to ischemic heart disease) in the mTOR inhibitor group and 7 patients died (5 due to cancer progression and 1 due to sepsis) in the non-conversion group." (PMID 28160552, 2017). "Among the 15 patients who received mTOR inhibitors after PTLD (11 from conversion while 4 already on mTOR inhibitors before cancer), 11 patients died (9 due to sepsis, 1 due to ischemic heart disease, 1 due to cancer progression)." (PMID 29228580, 2017). "As mTOR is a central driver of the sepsis‐induced decrease in protein synthesis, its kinase activity was assessed by quantifying the phosphorylation of its downstream substrates, 4E‐BP1 and S6K1." (PMID 27811170, 2016). "Acute sepsis decreased the in vivo rate of skeletal muscle protein synthesis and the phosphorylation of the mTOR substrate 4E‐BP1." (PMID 27811170, 2016). "Severe sepsis significantly increased heart calpain-1 levels and promoted ubiquitin and Pa28β over-expression with a reduction in the mTOR levels." (PMID 27880847, 2016). "The sepsis-induced increase in eEF2 phosphorylation in muscle of WT mice was consistent with the reduction in mTOR activity and global protein synthesis observed in these animals." (PMID 24945486, 2014). "As our previous work proved, deletion of mTOR decreased ERS-apoptosis of CD4 + T cells in sepsis." (PMID 41653334, 2026). "Therefore, our present study confirmed that PTEN/AKT/mTOR regulates cell activity, apoptosis, and autophagy in BBB injuries caused by sepsis." (PMID 39833662, 2025). "Furthermore, autophagic-lysosomal disorder modulated by mTOR pathway was proved to play vital roles in sepsis and SAI." (PMID 40933998, 2025). "Studies have shown that in the early stage of excessive inflammation in sepsis, the expression of glycolysis-related genes and key regulatory molecules (mammalian target of rapamycin, mTOR, hypoxia inducible factor-1α, HIF-1α) in peripheral blood mononuclear cells is significantly upregulated." (PMID 41209006, 2025). "By targeting key pathways such as PI3K/Akt/mTOR and HIF-1α, and integrating the role of the microbiome, more effective and personalized treatment strategies can be formulated to address the complex metabolic challenges associated with sepsis." (PMID 41041277, 2025). "Similarly, liensinine regulates the PI3K/AKT/mTOR signaling pathway, significantly inhibits cardiomyocyte apoptosis, and enhances antioxidant defense ability, thereby improving sepsis-related myocardial dysfunction and reducing myocardial damage." (PMID 41244772, 2025).
Sepsis (continued). "Mammalian target of rapamycin (mTOR) is also decreased in lymphocytes of sepsis patients." (PMID 41158471, 2025). "More recently, a novel immunosuppressive effect of IFN-γ and mTOR signaling in septic animal models was described; during sepsis, activated NK T-cells stimulate secretion of IFN-γ by NK cells in a mechanism mediated by mTOR resulting in impairment of macrophage phagocytic function." (PMID 40076848, 2025). "In a model of sepsis-induced neuroinflammation, hydrogen has been shown to decrease the polarization of M1-type microglia while increasing the polarization of M2-type microglia through the modulation of mTOR-autophagy-dependent pathways." (PMID 40336538, 2025). "So, we hypothesized that mTOR pathway could regulate the intensity of ERS apoptosis through modulating autophagy in elderly sepsis patients, and played important roles in the occurrence of SAI and severely affected the prognosis of these patients." (PMID 40933998, 2025). "Whether mTOR/P70S6K signaling pathway regulates the expression of HIF−1α in intestinal epithelial injury in sepsis remains to be further studied." (PMID 38654163, 2024). "Sum up, high-dose VC may potentially result in inhibition of the PI3K/AKT/mTOR pathway in sepsis, reducing myocardial apoptotic damage and inflammatory storm, increasing autophagy, and ultimately protecting the myocardium." (PMID 38643461, 2024). "But, mTOR signaling is inhibited by sepsis and endotoxin-related inflammation." (PMID 38338123, 2024). "Further studies using HIF−1α gene knockout or overexpression technology could clarify the protective effect of the mTOR/HIF−1ɑ pathway on sepsis-induced intestinal mucosa injury." (PMID 38654163, 2024). "It has been suggested decreased protein synthesis mediated by inhibition of mTOR (mammalian target of rapamycin) may result in sepsis-induced muscle atrophy." (PMID 38178237, 2024). "In our study, based on the overall immune environment in sepsis, we first explored the effect of mTOR regulation of CTLA4 on overall CD4+ T-cell function, and further experiments and discussions are needed in the future on the function of different cell subtypes, such as Treg cells, Th17." (PMID 39104632, 2024). "The aim of this study was to clarify the relationship between expression level of CTLA-4 on CD4+ T cells and sepsis-associated immunosuppression (SAI), and to elucidate the possible mechanism of mTOR pathway mediated autophagic-lysosomal disorder in regulating CTLA-4 expression." (PMID 39104530, 2024). "Then, we could draw a conclusion that mTOR deletion restore CD4+ T-cell dysfunction in sepsis through alleviating CTLA4 accumulation by easing autophagy disorder." (PMID 39104632, 2024). "We finally provide that mTOR may be a potential target for sepsis treatment by alleviating autophagy disorder to reduce CTLA4 accumulation." (PMID 39104632, 2024). "Similar regulatory effects of mTOR in sepsis were demonstrated in our previous studies." (PMID 39104632, 2024). "Both cellular autophagy and apoptosis are modulated by the PI3K/AKT/mTOR signaling cascade, providing therapeutic leverage through the regulation of its constituent proteins to ameliorate the pathological state of myocardial injury in sepsis." (PMID 38784395, 2024). "Given such a regulatory relationship, targeting mTOR could provide new light to improve immune function in sepsis, and the prospect of using rapamycin in the clinic would be worth exploring further." (PMID 39104632, 2024). "mTOR is a key checkpoint in immune cell metabolism in sepsis." (PMID 37434129, 2023). "Recent studies show that PPAR‐γ/mTOR pathway may trigger autophagy and subsequent astrocyte‐mediated neuroinflammation in sepsis." (PMID 36922751, 2023). "It is speculated that IFNγ also reverses sepsis-induced immunosuppression through the PI3K/AKT/mTOR/HIF-1α pathway." (PMID 37434129, 2023).
Sepsis (continued). "Furthermore, 220 can serve as a reasonable therapeutic target for the clinical management of sepsis by acting as a decoy for 5100 as a ceRNA complex via the PI3K/AKT/mTOR axis." (PMID 37446388, 2023). "Since mTOR signaling is diminished in neonates, these findings could explain a higher prevalence of sepsis and sepsis-mediated death in neonates." (PMID 37762476, 2023). "First, the precise molecular mechanism by which XBJ affects the PI3K/AKT/mTOR pathway in sepsis remains unknown." (PMID 37219401, 2023). "Based on our results and previous literature we speculated that XBJ can safeguard the myocardium in septic rats by activating the PI3K/AKT /mTOR signaling pathway in the early stages of sepsis and inhibiting it in the latter stages." (PMID 37219401, 2023). "Furthermore, another study suggested that post-sepsis immunosuppression depends on the regulation of mTOR/IFN-γ in NK cells by NKT cells." (PMID 36817458, 2023). "Similarly, inhibition of the mTOR signaling pathway facilitates autophagy, ultimately alleviating cardiomyocyte dysfunction in sepsis." (PMID 38161332, 2023). "High level of SIRT3 protects against sepsis-induced AKI by modulating AMPK/mTOR-mediated autophagy." (PMID 37215112, 2023). "Interestingly, the expression of the proteins p-AKT, p-PI3K and p-mTOR were significantly upregulated in the myocardium of rat with sepsis as compared with the Sham group at the same point of time (1d, 2d, 3d and 5d)." (PMID 37219401, 2023). "This research indicated that ω-3 PUFAs could alleviate CLP-induced inflammatory response and multi-organ damage in rats with sepsis by regulating the AMPK/mTOR signaling pathway; thus, may be used as a potential therapeutic agent for the treatment of sepsis." (PMID 36694426, 2023). "However, mTOR knockout mice displayed reduced expression of apoptotic proteins and less ER vesiculation and expansion than what was observed in the wild-type sepsis controls." (PMID 35915740, 2022). "This was because H2 could regulate the mTOR‐autophagy signalling pathway to attenuate sepsis‐induced neuroinflammation." (PMID 36308410, 2022). "mTOR plays a central role in inflammatory processes and sepsis." (PMID 36365096, 2022). "Thus, resveratrol has the potential to protect the myocardium in sepsis by activating the PI3K/AKT/mTOR signaling pathway and inhibiting the NF-κB signaling pathway and related inflammatory factors." (PMID 36483739, 2022). "On the basis of these results, we hypothesized that the mTOR pathway may also play a vital role in A-L fusion failure in CD4 + T cells during sepsis." (PMID 35435531, 2022). "This indicates that mTOR is activated by ERS to affect CD4+ T cell apoptosis during sepsis." (PMID 35915740, 2022). "The mTOR pathway influences CD4 + T cell survival during sepsis." (PMID 35435531, 2022). "Similarly, several studies have indicated that inhibiting mTOR signaling pathway can attenuate sepsis-induced organ dysfunction in rats." (PMID 35242787, 2022). "We revealed the engagement of mTOR target genes within H3K4me3-marked histone in neutrophils isolated from healthy individuals and stimulated in vitro with LPS or IL-10, as well as in neutrophils isolated from sepsis and periodontitis patients." (PMID 35757755, 2022). "Our results also revealed the role of mTOR in regulating A-L fusion in CD4 + T cells during sepsis." (PMID 35435531, 2022). "mTOR is a signaling pathway involved in cell survival, cell stress response, and protein synthesis that may be a key point in sepsis-induced cardiac dysfunction." (PMID 36365096, 2022). "mTOR responds to various stressors, such as tissue hypoxia, inflammatory mediators, and low energy availability, which are involved in cardiac impairment during sepsis." (PMID 36365096, 2022). "Furthermore, suppression of the PI3K/AKT/mTOR pathway can facilitate oxidative stress and reduce apoptosis in sepsis-induced AKI, indicating that targeting miR-212-3p can help to limit AKI progression." (PMID 36230932, 2022).
Sepsis (continued). "Importantly, the top enriched pathway among these CpG sites distributed genes was mTOR signaling pathway, which plays an important role in immunosuppression following sepsis." (PMID 35242787, 2022). "Given the complex regulation of ferroptosis by mTOR, rapamycin could offer new hope for sepsis by precisely regulating mTOR in sepsis, so that ferroptosis occurs or is restrained appropriately and timely." (PMID 35990689, 2022). "Given the addition of NaHS, there was a decrease in autophagic vesicles and increased autolysosomes visible under transmission electron microscopy in the CLP rat group, Taken together, we conclude that excessive autophagy induced by AMPK/mTOR in sepsis leads to myocardial dysfunction." (PMID 35815056, 2022). "To test this hypothesis, we constructed an mTOR knockout mouse sepsis model to study the role of mTOR." (PMID 35915740, 2022). "Herein, we assessed the role of this PI3K/Akt/mTOR pathway in the context of our murine sepsis model, revealing that AE treatment was sufficient to suppress LPS-induced upregulation of PI3K, Akt, and mTOR, thus indicating that this compound inhibited sepsis-related activation of PI3K signaling." (PMID 35978995, 2022). "Our results suggest that the mTOR–Akt–IRE1α–JNK signaling pathway may be a promising new target for clinical immunotherapy of sepsis with great research potential and value, providing a new direction for the immunotherapy of sepsis." (PMID 35759162, 2022). "The ability of mTOR to impact this important cellular process may help to reveal novel therapeutic targets in sepsis." (PMID 35435531, 2022). "Our findings suggest that the mTOR pathway may be directly related to sepsis-induced cardiac injury and proper modulation of mTOR may be a protective mechanism." (PMID 36365096, 2022). "Firstly, the mammallian target of rapamycin (mTOR) could be contributing to sepsis-induced metabolic disturbances in the liver." (PMID 33616039, 2021). "Evaluating the effects of sepsis on altering hepatic mTOR signaling will shed light on whether there is acute activation of this pathway during the resistance phase and whether it shifts toward inhibition during the tolerant phase." (PMID 33616039, 2021). "PDK1/mTOR signaling is an important regulator within the metabolic signaling; thus, we wonder if PDK1/mTOR could be one target during sepsis." (PMID 32774145, 2020). "In a sepsis model of cecal ligation and puncture, nicotinamide adenine dinucleotide NAD-dependent protein deacetylase SIRT3, a member of the mammalian sirtuin family of proteins, provided protection from sepsis-induced AKI through AMPK/mTOR-regulated autophagy." (PMID 31936109, 2020). "So we analyze whether the deletion of mTOR in the myeloid cells could regulate the survival of sepsis." (PMID 32774145, 2020). "Our results suggested that sepsis inhibits the PTEN-AKT/mTOR pathway." (PMID 32714974, 2020). "Therefore, we generated the mice of PDK1 and mTOR deletion specially on the myeloid system and analyzed the early shock and the late immunotolerance during sepsis." (PMID 32774145, 2020). "Overall, the mTOR complex deletion could aggravate the LPS-induced shock at the late stage of sepsis in the CLP mice, which is completely different with the PDK1 knockout." (PMID 32774145, 2020). "PDK1/mTOR signaling has been confirmed to regulate the metabolism of tumor, T cell, B cell, and NK cells but has rarely been associated with the myeloid cell metabolism especially in CLP-induced sepsis." (PMID 32774145, 2020). "Based on the description of mTOR as a central regulatory player in sepsis-driven metabolic disturbances we questioned whether the effects of iron perturbations were mediated through the mTOR pathway." (PMID 31832425, 2019). "Since the activation of mTOR is inversely correlated with autophagic activities, the result suggests that enhancing Beclin-1 signaling can suppress mTOR activation, thereby sustaining autophagy even under conditions of severe sepsis." (PMID 30744190, 2019).
Sepsis (continued). "MitoQ could protect sepsis-induced acute lung injury through the activation of the PI3K/Akt/GSK-3β/mTOR pathway in rats." (PMID 31815144, 2019). "In our study, we investigated whether MitoQ could play a role in sepsis-induced ALI through the PI3K/Akt/GSK-3β/mTOR signaling pathway and found that the PI3K/Akt/GSK-3β/mTOR pathway could be activated by MitoQ treatment." (PMID 31815144, 2019). "Our study demonstrated that MitoQ could protect sepsis-induced acute lung injury by activating the PI3K/Akt/GSK-3β/mTOR pathway in rats." (PMID 31815144, 2019). "The AMPK/mTOR can induce autophagy, which may be the first stage in the mechanism of sepsis-induced AKI." (PMID 30487750, 2018). "However, to the best of our knowledge, there is little data describing the role of the mTOR pathway during sepsis in the heart." (PMID 30050390, 2018). "mTOR is crucial in the switch to pro-inflammatory glycolysis that occurs in sepsis." (PMID 26917434, 2016). "HIF1α is central to the functional reprogramming of monocytes in sepsis whereby tolerance, tissue remodelling, and antimicrobial responses are controlled, while epigenetic reprogramming dependent on the Akt–mTOR–HIF1α pathway modulates an effective immune response to sepsis in mice." (PMID 26917434, 2016). "ALLN administration prevented sepsis-induced increases in calpain and ubiquitin levels in the heart, which resulted in decreased of structural and contractile proteins degradation and basal mTOR expression levels were re-established." (PMID 27880847, 2016). "Based on these results, it has become essential to assess the mTOR protein levels involved in the control of protein synthesis, metabolism and cell cycle in an attempt to correlate these findings with calpain-1 activation during sepsis." (PMID 27880847, 2016). "We identified regulatory genetic variants involving key mediators of gene networks implicated in the hypoxic response and the switch to glycolysis that occurs in sepsis, including HIF1α and mTOR, and mediators of endotoxin tolerance, T-cell activation, and viral defence." (PMID 26917434, 2016). "This higher Akt-mTOR-S6k signaling was unexpected, since phosphorylations at relevant sites of Akt, mTOR, 4E-BP, S6k and S6k's downstream substrate ribosomal protein S6 are decreased in muscles of different animal models of sepsis and burn injury." (PMID 21483870, 2011). "The controversial outcomes of mTOR inhibitors in sepsis clinical trials highlights the extreme importance of the intervention timing and immune-metabolic stratification of patients-inhibiting mTOR during the immunosuppressive stage may further impair T-cell function and exacerbate the condition." (PMID 41244772, 2025). "Its abnormal activation not only affects immune system function but also participates in the damage process of important organs such as the lungs and heart, suggesting that targeted regulation of the mTOR pathway may be a new therapeutic strategy for multi-organ protection in sepsis." (PMID 41244772, 2025). "Therefore, interventions targeting ERS or the mTOR pathway could provide potential therapeutic strategies for elderly sepsis patients." (PMID 40933998, 2025). "Additionally, the roles of targets such as CASP1/3, BCL2, and MTOR in sepsis have been discussed." (PMID 39584444, 2024). "The mTOR signalling pathway may play an important role in intestinal dysfunction in sepsis." (PMID 38654163, 2024). "Specific pharmacological inhibitors of the mTOR signaling pathway may be used for anti-inflammatory therapy in several inflammation-related diseases, such as cancer, neurodegenerative diseases, atherosclerosis, sepsis and rheumatoid arthritis." (PMID 38716051, 2024). "Additionally, we further exploited the associated regulatory pathways of CTLA4 accumulation in sepsis, and it was found that there was a close relationship between the mTOR signaling pathway, autophagy, and CTLA4 accumulation, and elucidated the mTOR-autophagy-CTLA4 regulatory axis." (PMID 39104632, 2024).